LSAMP (limbic system associated membrane protein)
Diseases named in the same sentence as LSAMP in open-access papers (continued):
Sharing a sentence is not in itself a finding about the gene and the disease.
schizophrenia (3 papers, 2014 to 2020). A major psychotic disorder characterized by abnormalities in the perception or expression of reality. "LSAMP (limbic-system-associated membrane protein) is a neuronal surface glycoprotein distributed in cortical and subcortical regions of the limbic system; it is involved in neurite formation and outgrowth, and it was previously related to schizophrenia and bipolar disorder." (PMID 33260921, 2020). "Growing evidence suggests that the IgLON family of neural adhesion molecules LSAMP, NTM, NEGR1, and OPCML are important candidates in forming the susceptibility to schizophrenia (SCZ)." (PMID 29434535, 2018). "Further, LSAMP and ZBTB20 have each been implicated in various brain regions associated with schizophrenia." (PMID 24650298, 2014).
lung adenocarcinoma (2 papers, 2021 to 2024). A carcinoma that arises from the lung and is characterized by the presence of malignant glandular epithelial cells. "Hypermethylation, copy number variation, and microRNA post-translational mechanisms were also investigated as possible regulatory mechanisms of LSAMP expression in lung adenocarcinoma." (PMID 39595156, 2024). "The expression levels of LSAMP and NTM in tumor tissues were lower than that in normal tissue samples of lung adenocarcinoma (LUAD); however, the levels of OPCML were relatively inconsistent." (PMID 34202934, 2021). "In an LSAMP gene expression study, a small set of lung adenocarcinoma samples was compared with non-malignant control samples, suggesting that LSAMP was expressed at lower levels in the cancer tissue." (PMID 39595156, 2024).
prostate tumor (2 papers, 2018 to 2024). "The chromosomal mapping of prostate tumor DNA breakpoints in a recent report pinpointed the LSAMP locus and its association with localized and metastatic castration-resistant prostate cancers." (PMID 39595156, 2024). "Further studies of structural variations in prostate tumors identified LSAMP as a candidate driver gene and possible prognostic target for AA tumors." (PMID 39595156, 2024). "We found that the LSAMP gene that is frequently deleted in ERG-negative prostate tumors of African American men49, was often rearranged including fusion with ZBTB20 specifically in the ERG-negative group." (PMID 30150711, 2018).
renal cell carcinoma (2 papers, 2014 to 2024). "Overexpression of LSAMP was shown to inhibit proliferation in a renal cell carcinoma cell line, whereas depletion of LSAMP promoted cell proliferation in osteoblasts." (PMID 24885297, 2014). "LSAMP was shown to have tumor suppressive activity in a variety of cancers, first in renal cell carcinoma, where the LSAMP gene was found to be collocated with VHL on chromosome 3, with decreased LSAMP expression observed in nearly all the tumor samples and cell lines of clear cell RCC." (PMID 39595156, 2024).
B-cell lymphoma (1 paper, 2025). "Top proteins specifically associated with germinal center-derived B-cell lymphoma risk included LSAMP, FDCSP, SERPINA9, CCL21 and CD40LG." (PMID 40894013, 2025).
cholangiocarcinoma (1 paper, 2024). A carcinoma that arises from the intrahepatic biliary tree (intrahepatic cholangiocarcinoma) or from the junction, or adjacent to the junction, of the right and left hepatic ducts (hilar cholangiocarcinoma). "We conducted WB validation on cancer tissues and adjacent tissues of 6 cholangiocarcinoma patients and found that the expression of LSAMP in cancer tissues was significantly higher than that in adjacent tissues." (PMID 39355132, 2024). "We have found that LSAMP is a key oncogene in cholangiocarcinoma, providing a theoretical basis for future treatment of cholangiocarcinoma." (PMID 39355132, 2024). "In addition, we conducted qRT PCR validation on cancer tissues and adjacent tissues of 15 cholangiocarcinoma patients and found that LSAMP expression was significantly higher in cancer tissues than in adjacent tissues (P<0.05)." (PMID 39355132, 2024). "Therefore, LSAMP is an important oncogene for cholangiocarcinoma." (PMID 39355132, 2024).
emotional instability (1 paper, 2023). "In addition, the functions of LSAMP, CPNE 6, SRCN1 and other proteins are all related to the growth and development of dendritic spines, which means that abnormal connection density between neurons may also lead to emotional instability and the development of emotional disorders." (PMID 37239235, 2023).
large cell carcinoma (1 paper, 2021). A malignant epithelial neoplasm composed of large, atypical cells. "In the Oncomine database, there were 6 (3 from LUAD, 2 LUSC and large cell carcinoma) and 1 LUAD cohorts showing downregulation of LSAMP and NTM genes, respectively." (PMID 34202934, 2021).
liver cancer (1 paper, 2024). An epithelial or non-epithelial malignant neoplasm that arises from the liver. "In liver cancer, tumor-associated neutrophils (TANs) stimulate miR-301b-3p to express, which subsequently inhibits the level of CYLD and LSAMP and upregulates chemokine (CXCL5), leading to a higher infiltration of TANs." (PMID 39525474, 2024).
metastatic disease (1 paper, 2024). "In malignancies, LSAMP may play a significant role as a tumor suppressor, the loss of which leads to more aggressive phenotypes and mortality from metastatic disease." (PMID 39595156, 2024). "In malignancies, LSAMP may play a significant role as a putative tumor suppressor, the loss of which leads to more aggressive phenotypes and mortality from metastatic disease." (PMID 39595156, 2024).
mood disorder (1 paper, 2024). A cognitive disorder a disturbance in which the person's mood is hypothesized to be the main underlying feature. "Similarly, the LSAMP gene’s association with mood disorders highlights the potential overlap in genetic pathways that may contribute to both vitiligo and MDD." (PMID 38888950, 2024).
neuroblastoma (1 paper, 2024). Neuroblastoma (NB) is the most common solid, extracranial childhood tumor. "For a dataset of 498 neuroblastoma tumors, decreased LSAMP expression was significantly associated with decreased event-free survival and overall survival." (PMID 39595156, 2024). "When LSAMP expression was silenced via short hairpin RNA, significantly increased cell growth was noted in neuroblastoma cell lines." (PMID 39595156, 2024). "Heterozygous rearrangements in 3q13.31 at the region of LSAMP were present in 17% of tumor samples, while 43% of neuroblastoma cell lines displayed segmental chromosomal alterations in LSAMP." (PMID 39595156, 2024).
Obesity (1 paper, 2023). Accumulation of substantial excess body fat. "In addition, PAS-SNPs have also been identified in other obesity-related genes: Abcc6 and Npc1 in the Fat line and Lsamp (limbic system-associated membrane protein) in the Lean line, as well as in Arhgap8 (Rho GTPase activating protein 8) in the Fat line, which is localised in the dominant Fob2." (PMID 36414820, 2023).
pulmonary hypertension (1 paper, 2024). Increased pressure within the pulmonary circulation due to lung or heart disorder. "Current findings support a function for long non-coding RNAs and microRNAs in the modulation of LSAMP expression in cell senescence, cancer biogenesis, addiction, and pulmonary hypertension." (PMID 39057097, 2024).
tumor (25 papers, 2010 to 2025). "The studies reviewed focused on different endpoints associated with LSAMP’s involvement in oncogenesis, including nodal metastasis, tumor stage, tumor aggressiveness, or rates of cell line growth." (PMID 39595156, 2024). "Studies of ovarian epithelial carcinoma reported that LSAMP was reduced in tumor samples and was a prognostic factor, associated with decreased survival." (PMID 39595156, 2024). "Lnc-LSAMP-1 is located nearby a tumor suppressor gene termed limbic system-associated membrane protein (LSAMP) serving as an important membrane protein." (PMID 35524253, 2022). "LSAMP encodes a neuronal surface glycoprotein, and the gene has also been suggested to be a tumor suppressor." (PMID 36306349, 2022). "They analyzed 102 LMCAD cases and 149 controls and found that polymorphisms in an intron of limbic system-associated membrane protein, a tumor suppressor gene, are associated with LMCAD [5, pages 443–453]." (PMID 25202455, 2014). "Additionally, the loss of heterozygosity of the LSAMP locus was found to be significantly associated with tumor development and occurred independently of LSAMP promotor methylation." (PMID 39595156, 2024). "Recurrent deletion of chromosome 3q13.31, centering on the LSAMP locus, was prevalent in Pca tumours from African American men compared with Caucasian American men and associated with rapid disease progression, suggesting the involvement of LSAMP in the pathogenesis of Pca." (PMID 35159022, 2022). "Additionally, the molecular mechanism by which LSAMP functions as a tumor suppressor gene by modulating known oncogenic pathways may provide new opportunities for treating patients with LSAMP associated malignancies." (PMID 39595156, 2024). "This miRNA suppresses limbic system-associated membrane protein (LSAMP) and cylindromatosislysine 63 deubiquitinase (CYLD), enhancing Liver-CSC stemness and tumor aggressiveness." (PMID 41438763, 2025). "Beyond its many roles in the limbic system, LSAMP has been suggested to function as a tumor suppressor in early studies." (PMID 39595156, 2024). "LSAMP, more so than any other member of the IgLON family, was associated with cancer aggressiveness, where lower levels of LSAMP expression resulted in increased nodal metastasis and more advanced tumor stage." (PMID 39595156, 2024). "Copy number variation and microRNA appeared to be unlikely contributors to LSAMP regulation, but the methylation of the LSAMP promotor resulted in decreased copies of LSAMP mRNA, increased nodal metastasis, and more advanced tumor stages." (PMID 39595156, 2024). "From a total number of tumor samples and cell lines that showed either the partial or full methylation of the LSAMP promoter, 60% had a subsequent decreased expression of LSAMP." (PMID 39595156, 2024). "In an analysis of nine CCRCC cell lines, 53 sporadic tumors, and four familial tumors, no mutations in LSAMP itself were discovered, but the downregulation of LSAMP expression was observed in nearly all the tumor samples." (PMID 39595156, 2024). "Recurrent deletions of the LSAMP locus have been reported in tumours from African American men, identifying an African-specific aggressive PCa subset." (PMID 36045381, 2022). "In summary, the expression of LSAMP was negatively correlated with tumor aggressiveness in both RNA and protein levels, which suggests that low expression of LSAMP is involved in tumor progression in LUAD." (PMID 34202934, 2021). "LOC285194 was previously shown to suppress tumor cell growth and is the antisense transcript of LSAMP that has been reported to be a tumor suppressor gene." (PMID 27317124, 2016). "By restoring the expression of LSAMP in a cell line with a homozygous deletion of the gene, the proliferation rate in vitro was significantly reduced and tumor growth in vivo was significantly delayed." (PMID 24885297, 2014).
tumor (continued). "We believe that LSAMP is a tumor suppressor gene in osteosarcomas and that LSAMP suppress tumors by reducing the proliferation rate of cancer cells, possibly through upregulation of one or more of the genes HES1, CTAG2 and KLF10." (PMID 24885297, 2014). "Our results add to these evidences as we showed reduced proliferation rate in vitro and inhibited tumor growth in vivo when the expression of LSAMP was restored." (PMID 24885297, 2014). "Of note, we also observed that LSAMP, a tumor suppressor (downregulated in 64% OS cases; deleted at single allele in 75% OS cases), was also induced in drug-treated Saos2 cells." (PMID 22957032, 2012). "Using the pQTS approach, we found that the PRS of BCC is associated with two different proteins at a Bonferroni correction threshold of 1×10−05 of which LSAMP was identified through trans-pQTS and is an immunoglobulin that has been shown to act as tumor suppressor in several different cancers." (PMID 41358317, 2025). "The chromosomal locus 3q.13.31, harboring LSAMP, had a deletion rate of 56% in the tumor samples." (PMID 39595156, 2024). "Moreover, the preprotein of LSAMP has been proposed to have tumour suppressor properties and a role in neuropsychiatric disorders." (PMID 38534778, 2024). "LSAMP has been recognized as a tumor suppressor in some cancers." (PMID 39355132, 2024). "Emerging lines of evidence have shown that LSAMP serves as a tumor suppressor in multiple cancers." (PMID 35524253, 2022). "In addition, the status of hypermethylation of LSAMP correlated with nodal metastasis and higher tumor stages." (PMID 34202934, 2021). "Furthermore, the reduced proliferation rate in vitro and inhibited tumor growth in vivo is further pointing to a tumor suppressor function of LSAMP." (PMID 24885297, 2014). "This contrasts with the currently understood action of LSAMP in other human adenocarcinoma models and the proposed suppressor role of LSAMP among other human malignancies, where LSAMP expression downregulates the RTK pathway and suppresses tumor growth." (PMID 39595156, 2024). "Hypermethylation in the promotor of LSAMP was found in the tumor parts of LUAD, which correlated negatively with LSAMP mRNA." (PMID 34202934, 2021). "On the contrary, the expression of LSAMP and NTM correlated negatively with nodal metastasis and tumor stage." (PMID 34202934, 2021). "LSAMP, a third neuronally relevant gene, was overexpressed in DEX males and is involved in neuronal growth and tumor suppression." (PMID 33528889, 2021). "Consistently, the protein expression of LSAMP and NTM of the CPTAC cohort revealed that tumor parts expressed lower levels of LSAMP and NTM protein in LUAD; furthermore, the levels of LSAMP and NTM protein were correlated negatively with tumor stage." (PMID 34202934, 2021). "Tumor-activated neutrophils release BMP2 to trigger the expression of miR-301-3p in HCC cells, which down-regulates LSAMP and CYLD expression to increase the stemness of HCC cells." (PMID 32632106, 2020). "Deletions involving the LSAMP locus were reported in 27% of AA compared with 13% of CA tumors in tumor copy number variation data, and in 26% of AA compared with 7% of CA patients by Fluorescence in situ Hybridization Assays (FISH) on tumor tissue microarrays." (PMID 39595156, 2024). "In RCC cell line models lacking LSAMP expression, activations or re-expression of LSAMP resulted in the suppression of tumor growth." (PMID 39595156, 2024). "Conversely, we found the previously identified PCa driver gene LRP1B (12/17) and new candidate genes TTC28 (16/27), CADM2 (12/16), LSAMP (11/16), EYS (16/18), PTPRD (12/18), PACRG (5/6) and PDE4D (12/17) to be predominately interrupted in tumours from African patients." (PMID 36045381, 2022).
tumor (continued). "LSAMP was identified as a new potential driver gene in this study; other studies also reported a significantly higher number of inter-chromosomal rearrangements and exclusive association of LSAMP deletion/rearrangement for African American tumours, including ZBTB20-LSAMP gene fusion." (PMID 36045381, 2022). "The subclone with LSAMP deletion (#27, yellow), occurring in approximately 60% of the T5 tumor at the time of surgical resection, was not retained either in the relapse or the organoids, illustrating continuous clonal evolution over time." (PMID 36306349, 2022). "To further validate the gene expression of OPCML, LSAMP, and NTM, we retrieved data from Oncomine and TCGA cohorts with analysis showing higher expression of OPCML and lower expressions of LSAMP and NTM in tumor tissues compared with normal tissue with statistical significance in LUAD." (PMID 34202934, 2021). "By western blotting, we investigated whether the LSAMP transcript was translated, which to our knowledge has not been done in tumor samples." (PMID 24885297, 2014). "Lower expression of LSAMP and NTM, but not OPCML, were found in tumor parts compared with normal parts in six LUAD patients, and this was validated by public datasets, Oncomine® and TCGA." (PMID 34202934, 2021).
cancer (11 papers, 2015 to 2025). A tumor composed of atypical neoplastic, often pleomorphic cells that invade other tissues. "Current data unanimously support the notion that the downregulation of LSAMP is associated with oncogenesis in multiple cancer types, as well as worse outcomes for patients." (PMID 39595156, 2024). "The inactivation of LSAMP has been understood as a cancer genomic event via deletion involving the LSAMP locus at chromosome 3q13.31, which occurs at significantly higher rates in tumors of patients of AA than CA." (PMID 39595156, 2024). "As a result, seven genes (FGF10, SERINE2, LSAMP, STXBP5, PDE5A, GLI2, FRMD6) were screened to develop the cancer associated fibroblasts (CAFs)-related risk signature (CAFRS)." (PMID 37280069, 2023). "Similar to our results, low expressions of CASS4 and LSAMP indicated poor prognosis in other types of cancers." (PMID 36506313, 2022). "There are various mechanisms of LSAMP downregulation in several cancers, by genomic rearrangements, most frequently deletions, epigenetic silencing, or potentially post-transcriptional or post-translational inactivation, each of which may be related to predisposition to disease progression." (PMID 39595156, 2024). "Deletions in many of our hotspot genes (e.g., NRXN1, PDE4D, WWOX, LSAMP, and NEGR1) are also found in numerous cancers where they likely represent the effects of perturbed replication and transcription." (PMID 25373142, 2015).
psychiatric disorder (5 papers, 2013 to 2024). A disorder characterized by behavioral and/or psychological abnormalities, often accompanied by physical symptoms. "Limbic system-associated membrane protein has been linked with a wide spectrum of psychiatric disorders in humans and with behavioral alterations in rodents." (PMID 24633737, 2015). "However, the two IgLON family members, Negr1 (IgLON4) and LSAMP (IgLON3), which showed more behavioral alterations in the KO mouse model, have been implicated in several psychiatric disorders." (PMID 38370417, 2024). "Recently, LSAMP has been linked with a spectrum of psychiatric disorders in humans." (PMID 24633737, 2015). "The impact of LSAMP protein on neurite outgrowth and neuronal connectivity has been established in a wide spectrum of psychiatric disorders in humans." (PMID 26136648, 2015). "As the four genes (CSMD1, PTPRD, LSAMP, and NPAS3), which remained significant also in the sex-specific analyses, have previously been implicated in other psychiatric disorders, pleiotropic effects could also be suggested." (PMID 39457114, 2024).
LSAMP also shares sentences with these, for which no sentence is quoted: depression (3 papers); adenocarcinoma (2); pancreatic cancer (2); renal carcinoma (2); anxiety disorder (1); atherosclerosis (1); autoimmune disease (1); bipolar disorder (1); gallbladder cancer (1); gastric cancer (1); glioma (1); melanoma (1); Meniere disease (1); myasthenia gravis (1); nervous system cancer (1); neurodegenerative disease (1); prostatic adenocarcinoma (1); sarcoma (1); vitiligo (1); Wilms tumor (1).